STAT3 (signal transducer and activator of transcription 3)
Diseases named in the same sentence as STAT3 in open-access papers (continued):
Sharing a sentence is not in itself a finding about the gene and the disease.
pancreatic cancer (continued). "Previous studies have stated that elevated MDSC levels were associated with reduced overall survival in patients with pancreatic cancer, and IL-6 produced by PSCs in TME could activate MDSC via JAK/STAT3 (Janus kinase/signal transducer and activator of transcription 3) signaling." (PMID 29254283, 2017). "Therefore, we further investigated whether RES and TRES inhibited cell proliferation and induced apoptosis in pancreatic cancer cells by suppressing STAT3 and NFκB signaling pathways." (PMID 27539371, 2016). "Therefore, targeting STAT3 by small molecule inhibitor FLLL32 could be a potential therapeutic strategy for inhibiting pancreatic cancer progression and overcoming chemo/radio-resistance." (PMID 26887043, 2016). "Since STAT3 serves as a point of convergence for numerous oncogenic signaling pathways, directly targeting STAT3 might be a more effective strategy for pancreatic cancer treatment, especially for overcoming chemo/radio-therapy resistance that derives from CSCs." (PMID 26887043, 2016). "Additionally, we found that inhibition of STAT3 or NFkB activation could also sensitize pancreatic cancer cells to gemcitabine." (PMID 27415424, 2016). "However, there is no data showing whether RES affects the nuclear translocation of STAT3 and NFκB in pancreatic cancer cells." (PMID 27539371, 2016). "Next examined whether UA modulates the STAT3 phosphorylation in pancreatic tumors." (PMID 26909608, 2016). "We found that UA inhibited proliferation of various human pancreatic cancer cells and potentiated the antitumor activity of gemcitabine through the inhibition of transcription factors NF-κB and STAT3 as well as multiple inflammatory gene products regulated by NF-κB and STAT3." (PMID 26909608, 2016). "In addition, we recently demonstrated the ability of Nx to reduce fibrosis in a pancreatic cancer model which may possibly occur through modulation of STAT3/NFκB/EP4 axis." (PMID 24796733, 2014). "To determine whether reduced STAT3 activation may be responsible for some of the effects of PKCζ KD, we assessed the effect of a pharmacological inhibitor of STAT3 on the transformed phenotype of pancreatic cancer cells." (PMID 24015205, 2013). "Furthermore, STAT3 activation was significantly reduced in PKCζ RNAi tumors when compared to NT RNAi tumors, indicating that PKCζ regulates STAT3 activation in pancreatic cancer cells both in vitro and in vivo." (PMID 24015205, 2013). "Our observation that inhibition of PKCζ expression significantly and stably reduced STAT3 activation in pancreatic cancer cells suggests that PKCζ inhibition may be a means to stably suppress STAT3 activity, and thereby enhance the sensitivity of pancreatic cancer cells to current chemotherapies." (PMID 24015205, 2013). "It was unclear whether it could also inhibit STAT3 phosphorylation in breast and pancreatic cancer." (PMID 23056374, 2012). "At first, we examined whether pancreatic cancer cell lines express Stat1, Stat3, and Stat6." (PMID 15714203, 2005). "It has been demonstrated that rhein can restore chemosensitivity in the SMMC-7721 liver cancer cell line to doxorubicin and in pancreatic cancer cells to EGFR inhibitors by inhibiting mitochondrial energy metabolism and the STAT3 pathway, respectively." (PMID 40572668, 2025). "Targeting both STAT3 and EGFR has been shown to disrupt the feedback loop between these proteins and inhibit pancreatic cancer progression." (PMID 40166646, 2025). "Similar mechanisms were observed in breast, pancreatic cancer and gastric cancers, where β-adrenergic signaling promoted VEGF and MMP expression and activated STAT3 and MAPK pathways, facilitating metastasis." (PMID 41009819, 2025). "Mechanistic investigations reveal that KRASG12D protein released by ferroptotic pancreatic cancer cells undergoes RAGE‐mediated macrophage uptake, activating STAT3‐dependent FAO pathways to promote M2 polarization." (PMID 40919133, 2025).
pancreatic cancer (continued). "In pancreatic cancer, ferroptotic cells release KRAS G12D, which polarizes macrophages to an M2 phenotype through STAT3 signaling, promoting immune suppression and tumor progression." (PMID 40919133, 2025). "In pancreatic tumor cells, lactate induces K63 lactylation of endosulfine α (ENSA-K63la), a crucial step that triggers STAT3/CCL2 signaling." (PMID 39883522, 2025). "TST strongly decreases STAT3 protein expression and phosphorylation, limiting GPX4 transcription and enhancing ferroptosis in pancreatic cancer cells, according to western blot tests." (PMID 40969276, 2025). "For instance, in pancreatic cancer, lactate enhances MDSC immunosuppressive activity via the GPR81–mTOR–HIF-1α–STAT3 axis, promoting tumor immune evasion and radioresistance." (PMID 40710349, 2025). "Finally, to further investigate whether CAF‐derived CTHRC1 activates the STAT3 signaling pathway in pancreatic cancer cells via LIF, we cocultured PDAC cells with conditioned medium from CTHRC1‐overexpressing CAFs (CAFs‐CM) in the presence of the STAT3‐specific inhibitor Stattic." (PMID 40751418, 2025). "miR-let-7b-5p is also enriched in pancreatic cancer cell-derived EVs and can promote lipid accumulation, upregulate FOXO and STAT3, and downregulate IRS1 and GLUT4 in C2C12 skeletal muscle cells, indicating a role in the development of insulin resistance." (PMID 41347018, 2025). "In pancreatic cancer, hypoxia-inducible factor-1α (HIF-1α) inhibits T cell activity via the GPR81/mTOR/HIF-1α/STAT3 pathway." (PMID 40650086, 2025). "The results of in vitro experiments revealed that rhein and erlotinib, when used in combination, inhibited the phosphorylation of STAT3 and EGFR in pancreatic cancer cell lines, thereby inhibiting the proliferation of pancreatic cancer cells." (PMID 40535810, 2025). "This included GLUT1 and HK2, which have been previously shown to significantly increase aerobic glycolysis in pancreatic cancer and are induced by KRAS and STAT3, respectively." (PMID 40647442, 2025). "Empirical data has evidenced that the strategic inhibition of targets such as Pin1, MEK, STAT3, ARG1 can significantly elevate the response rates of pancreatic neoplasms to anti-PD1 therapy, enable more pancreatic cancer patients to benefit from immunotherapy." (PMID 40433359, 2025). "Our results also demonstrate that genetic knockdown of STAT3 abrogates IXA4-induced reduction in myotube diameter, further suggesting that IRE1α/XBP1 signaling mediates muscle wasting during pancreatic cancer cachexia through the activation of STAT3 signaling." (PMID 40655023, 2025). "Emodin potentiates the anti-cancer effects of EGFR inhibitor on pancreatic cancer (PANC-1 and BxPC-3) cells by inhibiting STAT3 signaling, promoting apoptosis." (PMID 40490812, 2025). "Clinical trial results further confirmed that in patients with advanced pancreatic cancer, the expression levels of NF-κB, COX-2, and STAT3 in peripheral blood mononuclear cells (PBMCs) were significantly reduced following curcumin treatment." (PMID 41515171, 2025). "For example, the STAT3 inhibitor NSC74859 opposes PSC-induced migration and EMT-related markers (Snail and cadherin-2) expression in pancreatic cancer cells." (PMID 39195299, 2024). "It would appear that the STAT3 signaling pathway was the intended target for the anti‐EMT, anti‐invasion, and antimetastasis effects of quercetin in pancreatic cancer cells." (PMID 38690008, 2024). "For example, the STAT3 inhibitor Napabucasin (BBI608) was assessed under phase III clinical trials for gastrointestinal (GI) cancers, including pancreatic cancer." (PMID 38326371, 2024). "The STAT1, STAT3, EGFR, and Notch‐1 signaling pathways can be blocked to prevent the development of pancreatic cancer." (PMID 38690008, 2024).
pancreatic cancer (continued). "By upregulating their expression, STAT3 activation promotes cancer cell invasion, and STAT3 knockdown reduces MMP expression and pancreatic cancer cell invasiveness in mice." (PMID 38339245, 2024). "Studies have shown that the inhibition of IL-6/STAT3 signaling pathway reduces EMT and inflammation in pancreatic cancer cells." (PMID 39195299, 2024). "(A) Representative H&E staining of pancreatic tumor sections derived from KPC cells of the indicated genotypes, SMAD4 KO (n=12), SMAD4/STAT3 DKO (n=3) and TGFBR2/STAT3 DKO (n=3), where n denotes the number of mice injected." (PMID 38573819, 2024). "Curcumin has the ability to inhibit not only the protein phosphorylation of STAT1 and STAT3 but also the EGFR and Notch‐1 signaling processes, all of which play important roles in the progression of pancreatic cancer." (PMID 38690008, 2024). "In pancreatic cancer cells, LIF has been reported to activate the JAK/STAT3 pathway, which upregulates genes involved in cell proliferation and survival." (PMID 39451257, 2024). "Murine pancreatic cancer cells (KPC) were orthotopically implanted into the pancreas of wild‐type, IL‐6−/−, and hepatocyte STAT3−/− male and female mice." (PMID 38632714, 2024). "Transfection with miR‐199a‐3p increased the proliferation, invasion, migration, and drug resistance of pancreatic cancer cells by downregulating SOCS7, increasing STAT3 phosphorylation, and upregulating SAA1 expression." (PMID 39431622, 2024). "In pancreatic cancer, PAK4 maintains stem cell-like phenotypes and decreases chemosensitivity to gemcitabine toxicity by activating STAT3 signaling." (PMID 38238316, 2024). "The signal transducer and activator of transcription 3 (STAT3) are constantly activated via Ser705 phosphorylation to promote G1/S-phase progression and enhance the proliferation of pancreatic cancer cells." (PMID 37513375, 2023). "SRC and STAT3 signaling enhances the transcription of angiogenic genes (e.g., IL8, VEGF) in human pancreatic cancer cells, while inhibition of SRC activity decreases STAT3 phosphorylation and tumorigenicity." (PMID 37120696, 2023). "Immunofluorescence staining of the human pancreatic cancer tissues revealed that IL20RB and p-STAT3 were co-expressed in pancreatic cancer cells." (PMID 38098005, 2023). "Panaxadiol inhibits proliferation, and induced apoptosis of pancreatic cancer cells, and suppresses the growth of xenograft models by suppressing the JAK2/STAT3 pathway." (PMID 36814203, 2023). "To sum up, we discover that BA inhibits the expression of IL-6 and phosphorylation of AKT/STAT3 by mediating changes in miR-365/BTG2, thereby inhibiting the progression of pancreatic cancer." (PMID 37415745, 2023). "In pancreatic cancer, IGF-IR, STAT3, HIF-1α, IL-6, IGF-1, amongst others, have been described to be active and linked to the HSP90 pathways." (PMID 36966394, 2023). "IL-6/gp130/STAT3 signaling also has an established role in the aggressive and metastatic phenotype of PDAC and constitutes one of the essential signaling cascades in pancreatic cancer initiation and progression." (PMID 36495330, 2023). "For example, cucurbitacin I reduces the levels of p-JAK2 and p-STAT3 proteins and decreases the expression of CCND1 and CCNA2 in pancreatic cancer cells." (PMID 37958903, 2023). "It is reported that Sorafenib decreased constitutive STAT3 phosphorylation (Tyr705) as well as Mcl-1 and Bcl-xL expression in a dose-dependent manner to enhance TRAIL-mediated apoptosis in pancreatic cancer cell lines." (PMID 36975494, 2023). "BA inhibits the proliferation, migration, and invasion of pancreatic cancer cells in vivo and in vitro through inhibiting IL-6 protein expression and AKT/STAT3 protein phosphorylation by mediating miR-365/BTG2 axis." (PMID 37415745, 2023).
pancreatic cancer (continued). "As for pancreatic cancer, STAT3 contributes to KRAS-induced PDAC initiation and progression, and inhibition of JAK–STAT3 signaling results in the impairment of a progenitor cell phenotype and abrogation of tumor sphere formation capacity." (PMID 37743465, 2023). "As miR-302a-3p directly targets SOCS5 to boost STAT3 phosphorylation and induce the transcription of STAT3 target genes, SMARCA2 starts the miR-302a-3p/SOCS5/STAT3 signaling axis and thus potentiates pancreatic cancer metastasis." (PMID 37175555, 2023). "Let-7 also inhibits the progression of pancreatic cancer cells by upregulating the suppressor of cytokine signaling 3 (SOCS3) expression, leading to the inhibition of STAT3 phosphorylation." (PMID 38139352, 2023). "Blocking IL-6/STAT3 signaling by anti-IL-6 antibodies or STAT3 inhibitor (NSC74859) disturbed stellate cell-induced migration and expression of mesenchymal markers in pancreatic cancer cells." (PMID 35251963, 2022). "In pancreatic cancer, a natural small molecule, astaxanthin, acts via the HIF-1α/STAT3 axis to mediate RRM2, regulating the gemcitabine-induced EMT phenotype." (PMID 36678539, 2022). "MiR-301a is highly expressed in human pancreatic cancer patients, which can target SOCS5 to activate JAK/STAT3 and promote the migration and invasion of pancreatic cancer cells." (PMID 36291659, 2022). "Phosphorylated STAT3 can directly binds to the promoter region of ZEB1 and induces the transcription of ZEB1 in pancreatic cancer cells." (PMID 35372504, 2022). "As we also found significantly increased levels of IL-8 and IL-6 cytokine in the plasma of pancreatic cancer patients, we suppose this was probably through IL17/NFkB/STAT3 signaling." (PMID 35269689, 2022). "The combination of STAT3 and ICI provides a promising strategy to improve the efficacy of current immunotherapy for pancreatic cancer." (PMID 36291659, 2022). "For example, IL-35-promoted STAT3 activation, reduces the infiltration and function of CD8+ T cells in pancreatic cancer by inhibiting the expression of CXCR3, CCR5, and IFN-γ." (PMID 36291659, 2022). "Previous studies reported that the carcinogenic mechanism of ITGA2 is rarely involved in pancreatic cancer, except that blocking ITGA2 can improve tumor immune response by reducing the phosphorylation level of STAT3 and inhibiting the PD-L1 expression." (PMID 35193647, 2022). "As a key molecule in the mechanism of carcinogenesis, STAT3 plays a role in tumor cells and other cells in the TME of pancreatic cancer." (PMID 36291659, 2022). "We previously found that TA3, a steroidal saponin isolated from Anemarrhena asphodeloides Bunge, attenuates the suppression of SREBP-1 and induces G2/M cell cycle arrest via the STAT3 and MAPK pathways in pancreatic cancer." (PMID 36233202, 2022). "STAT3 is one of STAT proteins and a key element in promoting the growth of pancreatic tumors harboring oncogenic K-ras." (PMID 36173644, 2022). "It has been reported that phosphorylation of STAT3 (Tyr705) contributes to ZEB1 up-regulation, which in turn subsequently induces expression of integrin α3 and integrin β1 in pancreatic cancer cells." (PMID 35372504, 2022). "In order to better disclose the involvement of STAT3 and ABC transporter modulation by caryophyllane sesquiterpenes in Bx-PC3 pancreatic cancer cell proliferation and progression, the cell migration in the wound healing assay was studied." (PMID 35745837, 2022). "Schwann cells activated by pancreatic cancer cells released IL6, which activated STAT3 signaling and induced the EMT process in pancreatic cancer cells, thereby promoting the metastasis of pancreatic cancer cells." (PMID 36522730, 2022). "MBZ has been shown to inhibit multiple signaling pathways, including MAPK/STAT3, JNK, ELK/SFR, MYC/MAX, and NF-κB, leading to apoptosis, autophagy, and DNA damage in various types of cancer, including pancreatic cancer." (PMID 36500220, 2022).
pancreatic cancer (continued). "It has been described that there exists an inverse correlation between STAT3 and MEK signaling which mediates resistance to RAS pathway inhibition in pancreatic cancer." (PMID 35886918, 2022). "Our findings suggest that miR-301a activates two major cell proliferation pathways, Tsc1/mTOR and Gadd45g/Stat3, in vivo, to facilitate development of inflammatory-induced PanIN and maintenance of PSC activation and desmoplasia in pancreatic cancer." (PMID 35211358, 2022). "This is the first evidence that CuI inhibits the proliferation of pancreatic cancer cells by suppressing JAK2 and STAT3 signal transduction." (PMID 35517401, 2022). "In pancreatic cancer cells, mutant Kras elicited IL17 expression, possibly via the STAT3 signaling pathway." (PMID 35453676, 2022). "IL1ɑ secreted by pancreatic tumor cells and subsequent IL6/JAK/STAT3 activation in CAFs have been shown to trigger iCAF formation." (PMID 36109493, 2022). "For example, chemoresistance of pancreatic cancer has been attributable to hyperactivation of MAPK, STAT-3, and NF-κB signaling pathways." (PMID 33430324, 2021). "STAT3 and CASP3 were determined as specific hub nodes related to liver cancer, while NOTCH1 and CTNNB1 were characterized as the specific hubs of pancreatic cancer." (PMID 35154607, 2021). "Pancreatic cancer treated with CT, a selective STAT3 inhibitor, and Gefitinib (EGFR inhibitor) also showed encouraging results with the lowest time capable of inducing cell death in all eight pancreatic cancer cells examined." (PMID 33544704, 2021). "STAT3 and CASP3 were dysregulated in liver cancer; however, NOTCH1 and CTNNB1 were related to pancreatic cancer." (PMID 35154607, 2021). "Another study indicated that hyperglycemia induced tumor progression through increased levels of phosphorylated STAT3 and Myc proteins in KRAS-mutant pancreatic cancer in vivo." (PMID 34829591, 2021). "Collectively, the AE@NPs prepared in this study possess great potential for pancreatic cancer treatment by dual suppressing of EGFR and STAT3 pathways and activating ROS-responsive p38 MAPK pathway." (PMID 33815107, 2021). "The transcription factor STAT3 participates in the unique immunosuppressive pancreatic TME and pancreatic cancer progression in many ways through its activity in a variety of cell types, such as cancer cells and immune cells." (PMID 33722297, 2021). "To this end, we tried to develop poly (lactic-co-glycolic acid) (PLGA) nanoparticles to co-load Alantolactone (ALA, a novel STAT3 inhibitor) and Erlotinib (ERL, an EGFR inhibitor) for pancreatic cancer to test our guess." (PMID 33815107, 2021). "Overall, these data reveal that EPA reduces p-STAT3/HPS expression and ACC-1-mediated FA metabolism to inhibit the viability of SUIT-2 pancreatic cancer cells." (PMID 33801246, 2021). "A mechanistic study showed that knockdown of ciRS-7 inhibited the proliferation and invasion of pancreatic cancer cells with up-regulation of miR-7 through releasing sponge and down-regulation of EGFR and STAT3 pathways by miR-7." (PMID 34439315, 2021). "TSAIII can induce apoptosis and inhibit cell proliferation by suppressing the STAT3 and ERK1/2 pathways in human pancreatic cancer." (PMID 33799345, 2021). "The model simulations proposed the proteins AURKA, CD44, PAK1, STAT3, and TWIST1 as promising therapeutic targets for pancreatic cancer." (PMID 33578795, 2021). "Due to our published data demonstrating the synergistic effects of targeting the Ref‐1–STAT3 axis, we anticipated that APX3330 exposure would augment Rux‐mediated inhibition especially in models of pancreatic cancer that express high levels of Ref‐1 and STAT3." (PMID 33274592, 2021). "Blocking STAT3 axis by PS-Gp130 and MYC peptides inhibits tumor growth and increases tumor infiltration of cytotoxic CD8+ T cells in mouse pancreatic cancer model." (PMID 33491667, 2021).